MOG (myelin oligodendrocyte glycoprotein)
Diseases named in the same sentence as MOG in open-access papers (continued):
Sharing a sentence is not in itself a finding about the gene and the disease.
infection (continued). "We found a correlation between anti-myelin positivity and anti-HSV-2 IgG particles, but previous studies suggest anti-MOG antibodies’ peripheral presence preceding such infection." (PMID 35624969, 2022). "We found that the percentage of patients with a preceding infection was lower in children with MOG-IgG seropositive ADEM than in children with MOG-IgG seronegative ADEM (p = 0.023)." (PMID 35669399, 2022). "Infections, possibly by general immune cell activation or altering blood/brain barrier permeability, have been shown to frequently precede attacks in MOG-EM and AQP4-IgG-positive NMOSD." (PMID 33078290, 2021). "To compare CD8+ T-cell responses within the same host and thus tissue microenvironment, we performed co-transfer of naive Tox−/− and Tox+/+ P14 cells into WT and MOG-GP mice, one day prior to i.c. infection with rLCMV-GP33." (PMID 33579927, 2021). "We sorted brain infiltrating P14 cells from WT and MOG-GP mice both at early time point (day 7; WT mice: VE; MOG-GP mice: AE) and also at late time point (day 21; WT mice: VL; MOG-GP: AL) after infection." (PMID 33579927, 2021). "Possible explanations include: a direct CNS infection with leakage of CNS antigens in the periphery, and a secondary peripheral immune reaction against MOG; or a peripheral infection that stimulates MOG antibody production via molecular mimicry." (PMID 30555462, 2018). "We found that either ADE infection or direct infection exhibited similar levels of virus binding and absorption at all 3 sets of MOG." (PMID 26923481, 2016). "Infection with the MHV-A59 strain suggested that acute encephalomyelitis provides a milieu capable of supporting proliferation of transferred MOG-specific T cell receptor (TCR) transgenic T cells within the CLN." (PMID 26559484, 2015). "In this study, we show that, after infection with Plasmodium berghei NK 65, MOG-immunized mice develop an aggravated form of Experimental Autoimmune Encephalomyelitis." (PMID 25329161, 2014). "In this context it was recently shown that demyelination is augmented in an animal model of virally induced mild demyelination if the animals are engineered to produce anti-MOG IgG prior to infection." (PMID 22093619, 2011). "We speculate that this infection may have triggered an immune response, resulting in the patient’s positive MOG and GFAP antibodie." (PMID 41333477, 2025). "The association between MOG-IgG and prior infections may indicate that previous infections could be a potential trigger for MOG-OPN." (PMID 41235231, 2025). "These infections may trigger immune responses against MOG antigens through various mechanisms, including molecular mimicry, bystander activation, or epitope spreading." (PMID 41235231, 2025). "All had recovered from the infection by the time they were hospitalized for MOG-ON/AQP4-ON." (PMID 38988608, 2024). "The purpose of this work was therefore to further analyze the effect of LDV infection, and to specify which types of DCs were affected by the infection and whether the specific T cell response against the MOG peptide was actually suppressed." (PMID 38732169, 2024). "Through an impaired BBB (provided by activated T cells, infections, coexisting autoantibodies etc.), these MOG antibodies could enter the perivascular spaces and CNS, where they could contribute to disease pathology." (PMID 36925938, 2023). "Although a high frequency of patients who were seropositive for isolated MOG-IgA showed records of attacks preceded by infections or vaccinations, we did not observe associations with specific triggers." (PMID 37548987, 2023). "Infections, molecular mimicry, and MOG peptide presentation could facilitate the activation of self-reactive T cells." (PMID 36925938, 2023). "In addition, we observed that between 21 to 35 days after infection (contraction-memory phase) the ratio of Tox−/− to Tox+/+ P14 cells in the CNS continued to drop over time in MOG-GP recipient whereas it remained stable in WT recipient mice." (PMID 33579927, 2021).
infection (continued). "In addition, we found that TOX expression was higher in the memory-like TCF-1hi subset, a trend which was already noticeable 7 days after infection of MOG-GP mice." (PMID 33579927, 2021). "There are several reports of MOG antibody-positive ON followed by prodromal infections." (PMID 34106635, 2021). "We hypothesized that a subset of antigen-presenting cells, as a result of a direct infection or under the influence of other signals received by other immune cells during the infection, were able to skew a Th1 phenotype upon MOG presentation." (PMID 22615572, 2012). "This indicates that pending exceptions, these titers are quite stable over time, excluding titer variability at blood sampling (for example, elevated total IgG due to infection) and that few blood sample measurements would be necessary to define the level of anti-MOG antibody reactivity." (PMID 22093619, 2011). "Additionally, infections may disrupt the blood-brain barrier, exposing MOG antigens to the peripheral immune system and activating B cells to produce MOG antibodies." (PMID 41235231, 2025). "Thus, in patients with a clinical presentation suggestive of MOGAD and with immunosuppression, MOG seropositivity (especially at low titers) should be interpreted cautiously and a thorough work-up for alternative aetiologies (like infections) should be completed." (PMID 37845760, 2023). "The infection preceding the first episode of ON might have facilitated the onset of MOG-EM." (PMID 33078290, 2021). "However, the exact relationship between infection or vaccination and MOG-IgG-positive EM is unknown." (PMID 27793206, 2016). "MOG-Abs are produced mostly peripherally, and these Abs can penetrate the impaired BBB (induced by activated T cells, infection, and co-existing autoantibodies)." (PMID 39408955, 2024). "Because AAV-mediated gene expression in RGCs normally takes at least 2 weeks after infection, CHOP inhibition and XBP-1 activation are likely to occur 2–3 weeks after MOG immunization." (PMID 28726788, 2017). "Preceding infections, reported in 20–57% of MOGAD cases, are thought to facilitate antigen recognition and disrupt self-tolerance through mechanisms like molecular mimicry, bystander activation, or exposure of normally sequestered MOG antigens in the CNS." (PMID 41153632, 2025). "Our study showed that a higher proportion of the MOG-OPN group had abnormal CSF WBC counts (37.5% vs. 4.5%; P = 0.048) and the MOG-OPN group had a higher proportion of participants with previous infections (62.5% vs. 8.0%; P = 0.004), which suggests a more pronounced inflammatory response in vivo." (PMID 41235231, 2025). "Due to infections being commonly reported in MOGAD, the hypothesis of post-infectious generation of MOG-specific antibodies has been suggested." (PMID 39295869, 2024). "Infections also frequently precede relapses in both NMOSD and MOG-EM/MOGAD; taking into account both the first attack and subsequent attacks, NMOSD attacks were preceded by infections in around 30% of AQP4-IgG-positive and 20% of AQP4-IgG-negative cases in a large European study." (PMID 37022481, 2023). "The ADEM presentation, MOG antibodies and absence of an identified active infection were consistent with a diagnosis of MOGAD." (PMID 37845760, 2023). "The laboratory tests revealed a normal complete cellular blood count, without any signs of inflammation or infection, except for both cryoglobulins and IgG anti-MOG antibodies." (PMID 35626851, 2022). "MOG-Ab-positive children experienced more prodromal infections than did MOG-Ab-negative children (P < 0.05)." (PMID 36401212, 2022). "Among the MOG-Ab-positive children, ten (33.3%) exhibited symptoms of prodromal infection, compared to three patients (5.0%) in the MOG-Ab-negative group (P < 0.05)." (PMID 36401212, 2022).
infection (continued). "A higher proportion of precursor infection and relapse was found in MOG antibody-positive children than those in MOG antibody-negative ones, and the difference was statistically significant (P < 0.05)." (PMID 31507515, 2019). "The similar IFN-γ and IL-17 levels in the MOG-stimulated spleen cultures from the three experimental groups suggest that previous infection is not down-regulating the peripheral production of encephalytogenic cytokines." (PMID 24401094, 2014). "Notably, a higher percentage of MOG-ON patients had a history of preceding nonspecific infections, with 73.1% reporting such an occurrence before symptom onset." (PMID 38988608, 2024). "Furthermore, although we identified a B cell reactive to MOG and T. pallidum, we cannot rule out the involvement of additional coexisting infections in these patients." (PMID 39295869, 2024). "However, it should be taken into account that the onset of NMOSD (and MOG-EM/MOGAD) is not uncommonly preceded by a common cold or other infection." (PMID 37022481, 2023). "Interestingly, the enhancement activity of DENV-ADE infection is dependent on the final antibody concentration rather than the DENV/antibody ratio in all three MOG sets, as they all exhibited the same peak enhancement at an antibody dilution of 1/64." (PMID 26923481, 2016). "In this study, there were six times as many MOG-Ab-positive patients with a history of prodromal infection as MOG-Ab-negative patients, and neurological symptoms occurred within approximately 1 week after fever, which suggests that prodromal infection may play an important role in MOGAD." (PMID 36401212, 2022). "The two patients in this study developed the condition following infection, and tests for NMDAR, CASPR2, LGI1, AMPA, GABA, DPPX, mGluR, GAD65, MOG, GFAP, and AQP4 antibodies were all negative." (PMID 38765268, 2024). "Likewise, immunoblots performed on blocks of tissue isolated from mPFC, cerebellum, and hippocampus tissue of PBS- and IAV-inoculated mice indicated that infection did not alter abundance of MAG, MOG, or SOX10." (PMID 37596606, 2023). "In the case of EAE, LDV infection prior to MOG/CFA immunization blunted the production of IL-12 and IL-23 by cDC in the dLN, resulting in the absence of IFN-γ, IL-17, and GM-CSF production by MOG-specific CD4+ T cells, both in the periphery and in the CNS." (PMID 32265335, 2020). "To conclude, although infection with coronaviruses may in rare cases trigger MOGAD and we have for the first time identified an immunological (i.e. IgG) cross-reactivity between MOG and a viral nucleocapsid protein), our data do not support a strong association of coronavirus infections and MOGAD." (PMID 38576796, 2024).
neurological diseases (44 papers, 2011 to 2025). "Clinical syndromes associated with antibodies against myelin oligodendrocyte glycoprotein (MOG) are now recognized as a distinct neurological disease entity, and are gaining increasing attention." (PMID 38804311, 2024). "This case underscores the critical importance of precision in diagnostic procedures to ensure accurate identification and subsequent tailored treatment for MOG-AD, avoiding potential pitfalls associated with its resemblance to other neurological disorders." (PMID 38975430, 2024). "Future research should summarize more cases through clinical observation to clarify the possible association between MOG-IgG-associated neurological disorders and M. pneumoniae." (PMID 39334394, 2024). "Since the first reports of MOG-Ab associated neurologic diseases appeared just a few years ago, the floodgates of case reporting have been opened and our understanding of MOGAD has grown exponentially." (PMID 33013639, 2020). "In ABH mice, immunization with MOG and proteolipid protein readily induces neurological disease in which flaccid paralysis and preferential myelin loss is observed." (PMID 24053384, 2013). "MOG-IgG are rarely detected in patients with VZV infections associated with neurological diseases." (PMID 34737756, 2021). "Finally, the 82 samples negative in all live CBAs were from 24 patients with typical MOG-associated clinical phenotypes, MS, other neurologic diseases, and healthy controls." (PMID 32024795, 2020). "This work shows that BASY greatly improves neuroprotective characteristics in the MOG-induced murine model, suggesting a new way to prevent MS and other neurological disorders." (PMID 36771257, 2023). "We analyzed anti-MOG antibody titers, IgG subclass, and their cytotoxic ability in sera from patients with various neurological diseases." (PMID 36816137, 2023). "Thirty age-matched participants with AQP4–NMOSD, 17 participants with MOG antibody associated disease (MOGAD), and 15 participants with other neurological disorders (OND) were included as controls." (PMID 35413922, 2022). "In another study assessing MOG-IgG in all neurology patients admitted to hospital regardless of diagnosis, MOG-IgG was detected in approximately 1% of patients with other neurologic diseases and generally at low titer." (PMID 35785363, 2022). "To note, even with these precautions, low-titer false positive MOG-IgG can be encountered with other neurologic diseases, and clinicians should limit antibody testing to the cases with clinical and MRI features that are suggestive for MOGAD." (PMID 36330423, 2022). "In our study we systematically assessed the prevalence of MOG-Ab in adults with neurological disease by using live cell-based assay." (PMID 34262784, 2021). "Studies reporting the presence of myelin oligodendrocyte glycoprotein (MOG) antibodies (Abs) in patients with inflammatory demyelinating disorders in comparison to a control group of patients with other neurological disorders and/or healthy controls." (PMID 28533781, 2017). "Identified NF-L epitopes induced mild neurological signs similar to the observed with the NF-L protein, yet distinct from those characteristic of neurological disease induced with myelin oligodendrocyte glycoprotein." (PMID 24053384, 2013). "Aiming to identify biomarker allowing to predict relapse, we measured both myelin oligodendrocyte glycoprotein antibodies and neurofilament light chain levels in blood samples of patients that are known to reflect axonal injuries in neurological diseases including demyelinating autoimmune disorders." (PMID 36993944, 2023). "The present study demonstrates the occurrence of MOG-Ab in a wide range of neurological diseases." (PMID 34262784, 2021). "Another potential biomarker is MOG-IgG which can be present in sera from AQP4-IgG seronegative NMO patients and in other neurological disorders (ADEM, paediatric MS)." (PMID 26950113, 2016).
neurological diseases (continued). "According to current studies, MOG-IgG might be present in NMO, but also in other neurological disorders, including MS and ADEM, and even in some healthy individuals." (PMID 26950113, 2016). "Previous studies, including our own, have demonstrated that IgM and IgA antibodies have been detected against myelin basic protein (MBP), myelin oligodendrocyte glycoprotein (MOG), and other neural antigens in subgroups of patients suffering from MS and other neurologic disorders." (PMID 26290755, 2015). "Autoimmune antibodies to various protein targets, such as myelin oligodendrocyte glycoprotein (MOG), major basic protein (MBP), dipeptidyl-peptidase-like protein 6 (DPPX), and aquaporin-4, have been described and are even applied in the diagnosis of certain neurological disorders." (PMID 41009363, 2025). "Interestingly, false MOG-IgG positivity may occur in patients with various alternative neurologic disorders (e.g., neoplastic, genetic, metabolic, vascular) but seems rare in subjects without known neurologic diseases." (PMID 35785363, 2022).
tumor (38 papers, 2013 to 2025). "Cases of myelin oligodendrocyte glycoprotein (MOG) antibody‐associated disease (MOGAD) co‐occurring with neoplasms have been reported." (PMID 39932929, 2025). "In the present case, the early detection of MOG antibodies in the serum and CSF was crucial for establishing the diagnosis, underscoring the importance of MOG antibody testing in the differentiation of young patients presenting with tumor-like findings." (PMID 40904974, 2025). "Per the 2021 paraneoplastic neurologic syndrome (PNS) diagnostic criteria, MOG‐IgG is designated a low‐risk antibody, and rare cases of MOGAD with concomitant neoplasm have been reported." (PMID 39932929, 2025). "We retrospectively identified patients with MOGAD (i.e., compatible clinical phenotype and positive MOG antibodies analysed with a live cell-based assay) from 1/1/2015 to 1/1/2023 who had a neoplasm diagnosed within 2 years from MOGAD onset." (PMID 37360349, 2023). "Researchers primed synNotch-CAR-T cells through a highly tumor-specific neoantigen such as EGFRvIII, or a tissue-specific antigen such as myelin oligodendrocyte glycoprotein (MOG) in a GBM6 patient-derived xenograft model." (PMID 35326556, 2022). "The authors used the CNS- or tumor-specific antigens myelin oligodendrocyte glycoprotein (MOG) or EGFRvIII, respectively, as activating signal for the expression of anti-EphA2 or anti-IL13Ra2 CARs." (PMID 34884607, 2021). "NK cells also lysed oligodendrocytes or MOG-transfected tumor cells in vitro in the presence of MOG-specific, patient-derived serum antibodies." (PMID 30808363, 2019). "We demonstrate the rapid and specific clearance of antibodies recognizing the autoantigen, myelin oligodendrocyte glycoprotein and tumour target, HER2." (PMID 28561044, 2017). "Collectively, these results suggest that OGR1-KO mice are less able to mount T cell adaptive immune responses, regardless of the nature of the inciting antigen (i.e., ovalbumin, MOG, tumor cells, microbiota) or the Th bias of the disease model." (PMID 26828924, 2016). "In this large international cohort, concurrent neoplasm was identified in 3.6% of MOGAD patients within 2 years of MOGAD onset, but none demonstrated tumor MOG expression making any paraneoplastic association uncertain." (PMID 39932929, 2025). "Among the 7 non-tumor clusters, 5 expressed marker genes for immune cells including M2 TAMs, and 2 clusters expressed the brain-derived cell marker MOG." (PMID 38994023, 2024). "SynNotch receptors that identify particular priming antigens in GBM, such as the highly tumour-specific GBM neoantigen EGFRvIII or the CNS tissue-specific antigen myelin oligodendrocyte glycoprotein (MOG), can be employed to homogeneously trigger CAR production in tumors." (PMID 37304305, 2023). "MOG peptides could be present in the periphery, such as in cervical lymph nodes draining CNS, or rarely in a tumor expression MOG." (PMID 36925938, 2023). "We speculate that the lack of pathogenic effects of MOG-IgG may stem from suppression of pathogenic T-cell activity by tumor cells via PD-L1 expression or from elimination of pathogenic T cells by tumor-directed therapies." (PMID 41459522, 2025). "This case of an intracranial tumor with MOG-IgG positivity further suggests that the coexistence of MOG-IgG and tumor is not necessarily coincidental, and the pathogenic properties of MOG-IgG may shift over the course of disease." (PMID 41459522, 2025). "The absence of anti-MOG and aquaporin-4 antibodies, normal oligoclonal bands, and unremarkable CSF studies created a diagnostic scenario that directed us towards inflammatory demyelination rather than neoplasia." (PMID 41280952, 2025). "The syn Notch receptor that recognizes a specific priming antigen (EGFRvIII or MOG) and induces local expression of the CAR resulting in for tumor focused killing, high antitumor efficacy, and reduces exhaustion." (PMID 39364321, 2024).